IL17A (interleukin 17A)
Diseases named in the same sentence as IL17A in open-access papers (continued):
Sharing a sentence is not in itself a finding about the gene and the disease.
tumor (continued). "Importantly, the production of IL‐17A by tumor‐infiltrating γδ T cells mediates infiltration of MDSC in the TME, and BTNL2 blockade reduces MDSC infiltration." (PMID 38703051, 2024). "An increase in tumor-infiltrating IL-17A+ cells correlates with greater infiltration of anti-tumor mast cells and natural killer (NK) cells, alongside reduced infiltration of pro-tumoral M2 macrophages; greater infiltration of Th17 cells in tumors is associated with improved survival." (PMID 39676857, 2024). "Although the role of proinflammatory cytokine interleukin-17A (IL−17A) in malignancy contradicts existing data, some research shows that IL-17A could promote tumor growth." (PMID 39235230, 2024). "Notably, the neutralization of IL-17A through antibody-mediated methods has been shown to inhibit tumor development in this CAC model." (PMID 39906741, 2024). "As mentioned, this type of angiogenesis that initiates with IL-17A might also stimulate anti-tumor responses by creating a channel through new vessels to infiltrate immune cells and apply their anti-tumor activity into solid tumor tissues." (PMID 38515019, 2024). "High expression of IL-17A was also detected in the tumor tissue." (PMID 39906741, 2024). "Additionally, more M2-like macrophages (CD163+) accumulated into the tumor from mice with C. albicans infection and reduced after IL-17A neutralization." (PMID 37067414, 2023). "Although growing evidence suggests that IL-17A activity may drive resistance to anti-tumour immunotherapy and contribute to therapeutic failure, it is still unclear if blocking IL-17A could improve sensitivity to ICIs." (PMID 37483633, 2023). "Tumor multiplicity was also lower in IL-17A KO than in WT mice." (PMID 36125689, 2023). "High levels of IL17A in KRAS mutant mice promoted IL-6 and G-CSF secretion by binding to IL-17 receptor A on the surface of lung cancer cells, leading to increased invasion of tumor-associated neutrophils." (PMID 37670322, 2023). "Compared with the control group, the tumor size and weight of anti-IL-17A and anti-PD-L1 treatment groups were reduced to some extent, the growth rate was significantly slowed down, but the efficacy of the combined treatment was inferior to that of anti-PD-L1 monotherapy." (PMID 37978543, 2023). "IL-17A-mediated inflammatory response subsides postoperatively, but IL-17A concentrations remain elevated compared to the values in healthy controls, even after the removal of the tumor." (PMID 37427128, 2023). "In this assay, we observed that the colony formation ability of A549 and SPC-A-1 cells with high IL-17A expression was significantly enhanced, suggesting that IL-17A could promote tumor cell proliferation." (PMID 37978543, 2023). "Interestingly, IL-17A exhibited a noticeable decline from baseline to the point of maximum tumor remission." (PMID 38022654, 2023). "Researchers have found that low-dose radiotherapy of the tumor bed may increase the expression of IL-17A and promote invasive growth of the tumor by producing IL-6 and TGF- β." (PMID 37609436, 2023). "Activation of IL-17A signaling promotes self-renewal and immune escape of tumor stem cells." (PMID 37978543, 2023). "IL-17A promotes the expression of IL-6, G-CSF, MFG-E8, and CXCL1 in NSCLC tumor tissues to increase tumor-associated neutrophils (TANs) infiltration and reduce the number of tumor-infiltrating lymphocytes (TILs), leading to drug resistance to PD-1 inhibitors." (PMID 37978543, 2023). "One common mechanism that IL-17A–producing Vγ4+ and Vγ6+ cells share to foster cancer progression is the stimulation of granulopoiesis and recruitment of neutrophils to primary and secondary tumors that suppress anti-tumor CD8+ T cells." (PMID 36480166, 2023). "Accumulating evidence indicates that IL-17A activity may contribute to resistance to anti-tumor immunity and play a role in therapeutic failure." (PMID 38022654, 2023).
tumor (continued). "The impacts of IL-17A on VLA-4 in CD8+ T cell tumor infiltration require our further investigation." (PMID 37605139, 2023). "IL-17A has both an anti-tumor and pro-tumor effect in tumor lesions." (PMID 36851499, 2023). "γδT and Th17 cells are the two inflammatory cell types primarily responsible for the production of IL-17A in the tumour microenvironment, and the results display that the γδT cells (p = 0.0038 < 0.01) and Th17 cell (p = 0.0213 < 0.05) abundances in the IL17A-hi group were significantly higher." (PMID 37211606, 2023). "IL-17A–producing γδ T cells promote metastasis through expansion of neutrophils which in turn inhibit CD8+ T cells so that disseminated cancer cells subvert anti-tumor immunity." (PMID 36480166, 2023). "In addition, anti-ICOS treatment of tumor-bearing mice increased IL-17A expression by CD4+ T cells in the lung." (PMID 36480166, 2023). "Similarly, a decreased serum short-chain fatty acid (SCFA) level due to the loss of the gut microbiota Lactobacillus reuteri in HCC mice promoted the release of IL-17A by ILC3s in tumors, which boosted tumor growth." (PMID 36773210, 2023). "Treatment with dual ICI in combination with rm-IL-17A also decreased tumor growth (P = 0.0073 versus controls), whereas the addition of α-IL-17A strongly blocked the anti-tumor effect of dual ICI (P = 0.0130 versus dual ICI) and significantly shortened survival." (PMID 37525015, 2023). "However, IL17A also promotes the stromal production of substances that support tumor cell survival, proliferation, and angiogenesis." (PMID 38137417, 2023). "In this connection, it was demonstrated that IL-25, similar to IL-17A, could accelerate the proliferation and survival of tumor cells through the same oncogenic signaling pathways." (PMID 37835465, 2023). "The neutralization of IL-17A alleviated the tumor progression promoted by C. albicans infection." (PMID 37067414, 2023). "Thus, IL-17A also enhances proliferation and metastasis via inhibiting tumor apoptosis and suppressing antitumor immunity [i." (PMID 36993955, 2023). "Based on these results, IL-17A may promote the resistance of tumor cells to CRT, leading to tumor progression, recurrence, and metastasis." (PMID 37609436, 2023). "Antagonizing IL-17A alone may inhibit tumor progression, but in combination with immunotherapy may alter the tumor microenvironment to affect efficacy." (PMID 37978543, 2023). "successfully eradicated the tumor using combined PD-1 and IL-17A blockade." (PMID 37427128, 2023). "Interestingly, key factors known to induce immune evasion in tumor microenvironment, namely Foxp3 + (marker for T regulatory cells-Treg) and Il-17A were significantly increased in the esophagus of IL-1β transgenic mice compared to wild type littermates." (PMID 37543673, 2023). "IL-17A acts directly on CTLs in tumor microenvironment remains ambiguous." (PMID 37605139, 2023). "Tumor-derived AM promoted, via PI3K/Akt signaling pathway, mast cell degranulation, as well as favored tumor cell proliferation and the blockade of apoptosis in gastric cancer cells; these effects were reverted by blocking the release of interleukin-17A from mast cells." (PMID 36980580, 2023). "In our in vivo experiments, it can be found that blocking IL-17A alone can inhibit tumor growth to some extent, but when combined with anti-PD-L1 drugs, cancer tissue expression of PD-L1 is reduced, which makes anti-PD-L1 drugs lose their targets and the anti-tumor effect is diminished." (PMID 37978543, 2023). "The tumor tissues were examined for IL-17A expression by IHC." (PMID 37978543, 2023). "Abnormal generation of IL-17A mainly repressed tumor infiltration of stem-like exhausted CTLs." (PMID 37605139, 2023). "Positive IL-17A protein expression was observed in CRC compared to the non-tumour tissue." (PMID 37211606, 2023). "Pro-inflammatory cytokine IL-17A is highly expressed in a variety of tumor cells." (PMID 36795736, 2023).
tumor (continued). "Moreover, the frequencies of CD4+ and CD8+ T cells were significantly up-regulated in the tumor tissues, with substantial increases in IFNγ, TNFα and IL-17A expression in CD8+ T cells and augmented IL-17A expression in CD4+ T cells." (PMID 38074634, 2023). "Based on our experimental results, we hypothesized that IL-17A promoted NSCLC development by prompting the conversion of tumor cells to a pro-tumor growth phenotype and increasing PD-L1 expression." (PMID 37978543, 2023). "In vivo experiments, blocking IL-17A can slow down tumor growth." (PMID 37978543, 2023). "Chronic IL-17A activity-mediated production of inflammatory mediators mobilizes immunosuppression and recruits myeloid cells, creating an immune microenvironment suitable for tumor growth." (PMID 37978543, 2023). "However, addition of rm-IL-17A significantly slowed down tumor growth (P = 0.0487 versus control, P = 0.0016 versus dual ICI)." (PMID 37525015, 2023). "Neutralizing IL-17A could restore the tumor infiltration of ''stem-like exhausted'' CTLs and enhance the anti-PD-1-mediated antitumor efficacy." (PMID 37605139, 2023). "IL-17A is also involved in the growth of multiple tumor types and oxidative stress." (PMID 36125689, 2023). "However, when both IL-17A and PD-L1 were simultaneously inhibited, tumor cells expressed less PD-L1 and anti-PD-L1 losed its target, leading to a decrease therapeutic effect." (PMID 37978543, 2023). "It has been reported that IL-17A accelerates pancreatic acinar–ductal metaplasia, contributes to the maintenance of stem-like cancer cells, and recruits immunosuppressive granulocytes to the tumor site." (PMID 37686343, 2023). "Similarly, IL-17A has tumour-promoting effects mediated by promoting cancer epithelial-to-mesenchymal transition in vivo via tissue-remodelling matrix metalloproteinases (MMPs), such as MMP-2, MMP-7,and MMP-9." (PMID 37211606, 2023). "Interestingly, the ratio of TNFα+ CD4+ to IL-17A+ CD4+ T cells was also skewed towards more IL-17A+ CD4+ T cells in the tumor tissues versus STM while the ratios of IFNγ+ CD4+ and TNF+ CD4+ T cells showed a small change towards more TNFα." (PMID 38074634, 2023). "Furthermore, IL-17A promotes the immunosuppressive activity of Treg cells, resulting in tumour progression." (PMID 37483633, 2023). "It should be noted that IL-17A can also play an anti-tumor role, depending on the type of cancer." (PMID 35406557, 2022). "The expression of IL17A was significantly decreased in tumor tissues from HNSCC." (PMID 35902909, 2022). "Our study is the first to investigate the association between IL-17A mRNA and CRC prognosis based on the data of patients from all tumor stages (except for the GSE103479 and GSE75500 datasets that included only stage II and III patients, and GSE87211 that did not include tumor stage data)." (PMID 36098359, 2022). "Conversely, intravenous injection of recombinant IL-17A led to an increase in tumor volume." (PMID 35281021, 2022). "The correlation between IL17A and tumor-infiltrating immune cells (TIICs) was also determined." (PMID 35902909, 2022). "Mechanistically, inhibition of γδ T cells substantially reduced tumor development and IL-17A level." (PMID 36000726, 2022). "Moreover, lactate acts as an intrinsic inflammatory mediator, promoting the synthesis of interleukin (IL)-17A by T cells and macrophages, thus promoting chronic inflammation in the tumour microenvironment." (PMID 35990657, 2022). "MDSCs are recruited by various tumor-derived chemotactic factors, including IL-8, IL-17A, and CCL3." (PMID 35406557, 2022). "Moreover, recombinant strain of L. lactis that secreted biologically active IL-17A cytokine was also established, which made 26% of treated mice tumor-free in the TC-1 tumor challenge." (PMID 35757741, 2022).
tumor (continued). "Interestingly, infiltration of CT26 and A20 tumours by γδT17 as well as serum IL-17A concentration were all greatly reduced following anti-BTNL2 mAb treatment compared to treatment with isotype control antibody." (PMID 35017553, 2022). "Moreover, significantly lower survival was observed in patients with CRC who were found to have increased infiltration into the IL-17A tumor." (PMID 36422171, 2022). "The CCA results indicated that tumor volume (P = 0.021), γδ T (P = 0.016), IL-17A (P = 0.044), IFN-γ (P = 0.033), and TLR4 (P = 0.01) were significant factors for the microbial community, implying that these factors are associated with the oral microbial community." (PMID 36000726, 2022). "Furthermore, evidence for the tumor-promoting role of IL-17A and IL-22 in UC-CRC was also verified in vivo." (PMID 36135048, 2022). "Interleukin-17A (IL-17A) is produced by Th17 cells which infiltrate the tumor microenvironment and induces the expression of several inflammatory cytokines including IL-1β, IL-16 and IL-23, leading to variable effects on tumor growth at different stages." (PMID 36135194, 2022). "The combination therapy could elevate IFN-γ and TNF-α and decrease IL-17A in the serum of the tumor-bearing mice, which may contribute to the increase of TILs and the antitumor immunity." (PMID 35873573, 2022). "IL-17A is a proinflammatory cytokine with known pro and anti-tumor effects." (PMID 35924165, 2022). "Next, we found that the concentrations of IL‐17A in tumor tissues or TTSC were significantly increased when compared to that in non‐tumor tissues or NTCS and that there was clearly a positive correlation between IL‐17A production and FasL+ neutrophil infiltration within tumors." (PMID 34957697, 2022). "Recent reports have suggested that IL-17A could induce immunosuppression and facilitate tumor progression." (PMID 36499125, 2022). "IL-17A expressing Treg cells may cause CD8+ T cell exhaustion by IL-17A, which could accelerate colorectal carcinogenesis and tumour progression." (PMID 36569832, 2022). "In vivo, a dose of 3 μg nanobody per gram of body weight in tumor‐bearing mice could attenuate tumor progression and suppress excessive circulating levels of IL‐1a, IL‐2, IL‐10, IL‐12, and IL‐17A pro‐inflammatory cytokines." (PMID 34694686, 2022). "IL-17A, IL-17B, IL-17C, as well as IL-17F have been shown to promote tumor development, whereas IL-17D and IL-17E play anti-cancer roles in a context-dependent manner by activating the Nrf2 stress surveillance pathway, recruiting innate immune cells, and activating leukocytes." (PMID 36140808, 2022). "For example, it was reported that blocking interleukin 17A (IL-17A) could improve the tumor response to anti-PD-1 immunotherapy in MSS CRC." (PMID 35383115, 2022). "Using CIBERSORT algorithm, we analyzed the ratio of immune-cell subsets in tumor infiltration, and established 22 types of profiles of immune cells from PC samples (276 tumor samples with p < 0.05) to demonstrate the relationship of immune microenvironment with IL-17A/CTSK." (PMID 36138018, 2022). "Together with clinical correlation analysis, our data suggested that IL17A may play a tumor repression role in HNSCC patients." (PMID 35902909, 2022). "Staphylococcous epidermidis, a common skin commensal microbe, when restored in germ-free mice has been shown to normalize IL-17A production, a chemokine which may a play a role in tumor growth and anti-tumor immunity." (PMID 35474500, 2022). "IL-17A can also enhance tumor growth in vivo through the induction of IL-617." (PMID 35136076, 2022). "After activating the myeloid differentiation factor 88 (MyD88), the invading commensal bacteria and their products interact with TLRs on tumor-infiltrating myeloid cells, leading to the production of inflammatory cytokines such as IL-23 activating the production of IL-6, IL-22, and IL-17A." (PMID 35565269, 2022).
tumor (continued). "Thus, the role of IL-17A needs to be re-recognized in coordination with changes in the tumor immune microenvironment." (PMID 35523765, 2022). "Furthermore, despite the low number of these T cells, histological analysis of representative sensitive and resistant tumors confirmed detectable levels of IL-17A protein throughout the tumor with increased relative abundance in DOX sensitive tumors." (PMID 35924165, 2022). "Consequently, treating the tumor-inoculated mice with a combination of anti-IL-17a and anti-PD-1 eliminated 80% of the tumors." (PMID 35757757, 2022). "While the other studies revealed the anti-tumor effect of IL17A." (PMID 35902909, 2022). "In addition, many studies have demonstrated the overexpression (at mRNA and functional protein levels) of the cytokines IL-17A, IL-17F, IL-21 and IL-22 in the tumor nest in patients with CRC compared to nearby unaffected intestinal mucosa." (PMID 36422171, 2022). "Furthermore, we found that Vγ1 γδ T cell depletion decreased IL-17A secretion by CT26 tumour-infiltrating cells, with similar IL-17A secretion seen after treatment with anti-BTNL2 and controls." (PMID 35017553, 2022). "Our findings on the other hand are based on the IL-17A mRNA levels in both tumor and stromal cells." (PMID 36098359, 2022). "Interestingly, 48 h after pulsing, only anti-IL17A mAb-treated WT BMDM still showed the ability to take up CSFE+ tumor cells." (PMID 33802061, 2021). "More important, within in vivo GC models, our hypothesis that tumor‐activated B7‐H2+ neutrophils induce IL‐17A‐producing Th subset response and promote the progression of GC tumors has been fully verified." (PMID 34185422, 2021). "Moreover, modest staining with the anti-IL-17A antibody was seen inside and at the boundary of the tumor lesions." (PMID 34944746, 2021). "The tumor-promoting function of IL-17A is mainly manifested by angiogenesis and metastasis." (PMID 33707742, 2021). "Pro-tumor action of IL-17A was confirmed by numerous studies." (PMID 35008550, 2021). "In general, IL-17A-producing γδ T cells are considered to be tumor-promoting cells." (PMID 33707742, 2021). "Interleukin 17A (IL-17A) activity leads to a protumor microenvironment, dependent on its ability to induce the production of inflammatory mediators, mobilize myeloid cells and reshape the tumor environment." (PMID 33462141, 2021). "Regardless, mast cells might capture free IL-17A and serve as important reservoirs or vehicles for IL-17A in tumor beds." (PMID 33922465, 2021). "Moreover, we also found that increased IL‐17A expression and IL‐17A production were closely correlated with advanced tumor stage and increased tumor size." (PMID 34185422, 2021). "Mast cells contain many cytokines such as TGF-β and IL-17A in their granules and may have various effects on the tumor microenvironment by releasing these cytokines." (PMID 32488650, 2021). "MiR-19a mimic was also administered in the AOM/DSS-induced CRC mice and induced pro-inflammatory cytokines (IL-6, TNF-α, IL-1β and IL-17a), tumor proliferation marker (Ki-67) and NF-κB signaling markers (p-P65 and COX-2) via targeting TNF-α-induced protein 3 (TNFAIP3)." (PMID 33921348, 2021). "To further clarify the proposed “γδ T cells- IL17A- N2 neutrophils- immunosuppression” hypothesis, we examined functional changes in T cells in the tumor microenvironment." (PMID 34721375, 2021). "However, we observed that, in addition to Th17, other inflammatory cells express IL-17A in the tumor tissue." (PMID 34944746, 2021). "In the tumor microenvironment (TME), tumor-induced Foxp3-negative IL-17A+ Th17 cells decline in number at later time points, concomitant with the increase of “ex-Th17” Foxp3+IL-17A- suppressive tumor-associated Tregs." (PMID 34992594, 2021).